EGFR (epidermal growth factor receptor)
Diseases named in the same sentence as EGFR in open-access papers (continued):
Sharing a sentence is not in itself a finding about the gene and the disease.
adenocarcinoma (continued). "In particular, NSCLC with adenocarcinoma histology is characterized by epidermal growth factor receptor (EGFR) mutations, and it generally occurs more in non-smokers, females, and persons belonging to the Asia-Pacific region." (PMID 39727425, 2024). "In this study, overall EGFR mutations and subtypes other than exon 18 G719 X and exon 21 L861Q mutations were more frequent in women, non-smokers, and patients with adenocarcinoma, which is consistent with previous findings." (PMID 39364008, 2024). "Adenocarcinoma, a predominant histological subtype of NSCLC, often features mutations in EGFR." (PMID 39096122, 2024). "EGFR mutation occurrence was higher in demographic groups characterized by female gender, non-smoking history, adenocarcinoma subtype, and the presence of ground glass nodules." (PMID 38982267, 2024). "In this situation, clinical parameters such as Asian ethnicity, female sex, non-smoking status, and adenocarcinoma histology have been considered as potential prerequisites for the presence of EGFR mutation." (PMID 38539465, 2024). "NSCLC patients harboring the EGFR mutation exhibit distinct clinical characteristics, such as adenocarcinoma, female gender, never smokers, and Asian ethnicity." (PMID 39046176, 2024). "Demographic analyses have shown that a high prevalence of EGFR mutation is observed in women, nonsmokers, East Asian populations, and patients with adenocarcinoma, which is consistent with the findings of our study." (PMID 36806719, 2023). "In this study, there were 2.3% and 1.5% of the BRAF V600E mutation and BRAF V600 non-E mutation, respectively, among adenocarcinoma without EGFR/ALK alterations." (PMID 37374289, 2023). "EGFR mutations are rare in SCLC but may be slightly more common in combined SCLC, especially in cases of adenocarcinoma, and reports of response to anti-EGFR TKIs are available." (PMID 36769639, 2023). "In Asian females, non-smoking individuals with adenocarcinoma, EGFR mutations are common, and enhanced response to gefitinib, an EGFR inhibitor, has been reported in this patient population." (PMID 37310466, 2023). "Following the requirements of the NSCLC drug program in Poland, patients with adenocarcinoma did not have mutations in EGFR (epidermal growth factor receptor) or ALK (anaplastic lymphoma kinase) genes." (PMID 36688998, 2023). "Among the adenocarcinomas associated with non-smokers in East Asia, EGFR mutations are the most common driver genes, accounting for approximately 60-78% of driver genes in the group." (PMID 37033978, 2023). "Mutant EGFR was found to be significantly associated with the female sex, never-smoker status, lepidic predominant adenocarcinomas, and low or intermediate pathological grade." (PMID 37508774, 2023). "EGFR (Epidermal Growth Factor Receptor) gene mutations are present in 10–40% of patients and are predominantly detected in female patients with adenocarcinoma, in non-smokers, and in Asian patients." (PMID 37509393, 2023). "For example, EGFR mutations were more common in females, never smokers and in patients with adenocarcinoma." (PMID 37301854, 2023). "This conversion occurs mainly in non-smokers with EGFR-TKIs-sensitive mutations (e.g., EGFR ex19del/T790M mutation) in Asian adenocarcinoma patients." (PMID 37089959, 2023). "Additionally, p65BTK expression was substantially higher in epidermal growth factor receptor (EGFR) wild-type adenocarcinomas." (PMID 36903645, 2023). "While some studies have yielded similar findings, others have not definitively established a link between EGFR mutations and specific subtypes of adenocarcinoma." (PMID 38077251, 2023). "Mutations in EGFR genes are typically diagnosed in adenocarcinoma patients; they are ubiquitous among those with never-smoking status, female gender, and East Asian ethnicity." (PMID 36661704, 2023).
adenocarcinoma (continued). "Among 428 GGO pathological samples with pathologically confirmed adenocarcinoma, 262 (61.2%) GGO lesions had EGFR gene mutations, including 112 exon 19 deletions, 136 L858R missense mutations, 4 20INS insertion mutations, 3 G719X mutation and 3 L861Q mutations." (PMID 37340599, 2023). "EGFR-activating mutation mainly occurs in younger women and never-smokers with adenocarcinoma histology." (PMID 36786970, 2023). "Patient 3, a 68-year-old female never-smoker, had EGFR-mutated clinical stage IIa (cT2bN0M0) lepidic-predominant adenocarcinoma, for which she received gefitinib that was stopped after a month because of skin toxicity." (PMID 39790537, 2023). "The same recommendation is extended to EGFR mutation-positive NSCLC that had a higher incidence of BMs than in those with EGFR mutation-negative adenocarcinoma." (PMID 36786970, 2023). "All cases harboring a BRAF V600 mutation were adenocarcinoma without EGFR mutation and ALK translocation." (PMID 37374289, 2023). "An evaluation of therapeutically targetable mutations such as EGFR, ALK, and KRAS, as well as chromosomal rearrangement and fusion of EML4, identified increasing odds of presenting these mutations in adenocarcinoma and NS compared to NSCLC and smokers, respectively." (PMID 37686122, 2023). "The incidence of Her2 gene mutation in NSCLC is between 2% and 4%, and it is more frequent in non-smoker females with Asian ethnicity and adenocarcinoma subtypes similar to those seen in EGFR (Her1) mutations." (PMID 37340403, 2023). "According to the current study, there is a relatively high rate of EGFR mutation and sensitivity to EGFR-TKIs therapy in nonsmoking, adenocarcinoma, and female patients." (PMID 37390230, 2023). "Mutations in the epidermal growth factor receptor (EGFR) gene are identified in approximately 10–16% of NSCLCs, with a higher frequency among patients with adenocarcinoma and nonsmoking patients." (PMID 36571695, 2023). "Sex, adenocarcinoma histology, and never-smoking status are considered the most important factors associated with EGFR mutation." (PMID 37388220, 2023). "EGFR mutations are known to occur most frequently in adenocarcinoma in females, non-smokers, and the Asian population." (PMID 35626123, 2022). "Third, limited by the available biopsy specimens, we were unable to clearly determine whether the histological types other than adenocarcinoma had come from a post-EGFR-TKI treated transformation or from pre-existed mixed histology." (PMID 35888627, 2022). "The steepest survival increase has taken place after 2016, the time point where immunotherapy was implemented as a treatment option for the stage IV, adenocarcinoma population not harboring targetable mutations (EGFR/ALK)." (PMID 36523970, 2022). "Case #3 was a 29-year-old female with EGFR del19 adenocarcinoma." (PMID 36153311, 2022). "However, the specific imaging and pathological features of EGFR and ALK gene mutations in adenocarcinoma are still controversial." (PMID 35340157, 2022). "EGFR exon 19 deletion and L858R were more common in female patients and adenocarcinoma." (PMID 35061839, 2022). "This was the time point when immunotherapy was implemented as a treatment option for the stage IV, adenocarcinoma population not harboring targetable mutations (EGFR/ALK)." (PMID 36523970, 2022). "The EGFR and ALK genes mutated adenocarcinomas have specific imaging and clinicopathological features, and the mutations in exon 19 or exon 21 subtype have different imaging features, which is of great significance in guiding the clinical diagnosis and treatment of pulmonary nodules." (PMID 35340157, 2022).
adenocarcinoma (continued). "In addition, we also observed higher prevalence of EGFR exon 19 deletion and L858R both in female patients and in adenocarcinoma." (PMID 35061839, 2022). "Histological transformation in EGFR exon 19 deleted NSCLC (adenocarcinoma)." (PMID 35456982, 2022). "Mutations in the epidermal growth factor receptor (EGFR) tyrosine kinase domain occur more frequently in never smokers, the incidence of which is reported to be approximately 15% of adenocarcinoma cases and up to 62% in Asian populations." (PMID 36292049, 2022). "EGFR mutations are the most common in women with adenocarcinoma who have no history of cigarette smoking and are less common in elderly heavy-smoker patients." (PMID 36290461, 2022). "EGFR (Arg255Gln), EGFR (Ala647Thr), EGFR (Leu858Arg), KRAS (Gly12Cys), ALK (Pro254Thr), ALK (Trp288Ser), ALK (Glu797Lys), ROS (Glu1902Lys), PIK3CA (Met1043Ile), ROS (Leu567Val), and ROS (Phe1153Leu) mutations were present only in patients with adenocarcinoma." (PMID 36422072, 2022). "For NSCLC patients, EGFR mutations were reported to be more frequent in never-smokers, adenocarcinomas, patients of East Asian ethnicity, and females." (PMID 35624472, 2022). "Our findings are consistent with those of most existing studies that EGFR mutations were associated with female, non-smokers, and adenocarcinoma histology." (PMID 34807270, 2022). "There are some predictors for EGFR-TKI treatment response, including adenocarcinoma, never having smoked, and EGFR mutation-positive status." (PMID 35488047, 2022). "EGFR gene mutations are associated with several characteristics such as mutations more often in female patients, adenocarcinoma type NSCLC, non-smoker/smoking cessation patients, and East Asian patients." (PMID 36304376, 2022). "Moreover, patients with adenocarcinomas with positive epidermal growth factor receptor (EGFR) and anaplastic lymphoma kinase (ALK) alterations show improved survival compared to those without these alterations." (PMID 35455016, 2022). "Another Japanese study revealed that EGFR mutations were correlated with light smoking status and adenocarcinoma histology but not sex." (PMID 36341427, 2022). "Carriers of somatic ALK rearrangements do not respond adequately to EGFR TKIs despite displaying similar clinical characteristics to patients with EGFR mutations, including never exposure to smoke and adenocarcinoma histology." (PMID 36230877, 2022). "EGFR and KRAS mutations suggest a poor prognosis in adenocarcinoma patients." (PMID 35835908, 2022). "The EGFR gene test was mainly performed in patients with adenocarcinoma." (PMID 35954461, 2022). "Of note, a paired genomic analysis proposed, in a single center study, that an acquired genomic alteration in LKB1 through activation of the PI3K/AKT/mTOR pathway might favor the adenocarcinoma to squamous cell transformation after EGFR-TKIs." (PMID 36661676, 2022). "There was no statistical significance in BM rates of stage I and II patients between EGFR mutation-positive adenocarcinoma and EGFR mutation-negative adenocarcinoma (stage I, 1.8% (5/275) vs. 0.9% (3/335); stage II, 3.6% (1/28) vs. 6.9% (3/58))." (PMID 36457515, 2022). "A higher survival benefit (TTF or OS) was observed in no PD‐L1 expression than with PD‐L1 expression in adenocarcinoma, EGFR mutation, and ALK mutation patients." (PMID 34841687, 2022). "An investigation that enrolled 92 cases with unresectable stage III pulmonary adenocarcinoma reported that patients with EGFR-mutant adenocarcinoma who underwent upfront EGFR-TKIs had significantly superior PFS and OS than those who underwent upfront concurrent chemoradiation." (PMID 35806042, 2022). "A higher survival benefit was observed in no PD‐L1 expression than with PD‐L1 expression in adenocarcinoma, EGFR and ALK mutation patients." (PMID 34841687, 2022).
adenocarcinoma (continued). "The detection of EGFR mutations in the non-neoplastic epithelium around the adenocarcinoma indicates that EGFR mutations occur in the early stages of carcinogenesis." (PMID 35740676, 2022). "Even in stage IA adenocarcinomas, it is possible that this group may be candidates for adjuvant chemotherapy using EGFR-tyrosine kinase inhibitors." (PMID 35266536, 2022). "Immortalized cell line SW620, deriving from a human lymph node metastasis from an adenocarcinoma of the colon, was selected from a colon carcinoma library for its very low EGFR expression consistent with previous recent findings and low expression of the most common EGFR ligands, including TGFA." (PMID 35612280, 2022). "The frequency of EGFR mutations was higher in patients with adenocarcinoma than in those with non-adenocarcinoma (adenocarcinoma vs. non-adenocarcinoma, 48.1% vs. 18.5%, P = 0.023)." (PMID 35912248, 2022). "EGFR gene mutations were associated with several characteristics such as mutations more frequently in female patients, adenocarcinoma type NSCLC, non-smokers / those who had quitted smoking, and East Asian patients." (PMID 36304376, 2022). "Previous demographic analyses have shown that a high prevalence of EGFR mutation is associated with female, nonsmokers, adenocarcinoma tissue type, and East Asian populations, which is consistent with the our study results." (PMID 35422977, 2022). "The sample size is small, and we excluded patients with EGFR-mutant adenocarcinoma, resulting in a biased disease population, which might prohibit the direct generalization of our conclusion into other cohorts." (PMID 36277407, 2022). "Among 29 patients enrolled from May 2019 through August 2020, 21 (72.4%) had adenocarcinoma, 17 (58.6%) had a performance status of 2, 8 (27.6%) had asymptomatic brain metastases, and 13 (44.8%) had EGFR/ALK variations." (PMID 35372004, 2022). "Some authors assume that non-functional receptors result in the failure of therapeutics which target the EGFR extracellular domain, others report that the truncated EGFR isoforms may be predictive of the therapeutic response to Gefitinib in adenocarcinomas." (PMID 34356101, 2021). "Therefore, this study aims to explore the TIME in EGFR-mt adenocarcinoma and investigate the specific TIME features within different subgroups." (PMID 34136375, 2021). "Therefore, it is critical to determine EGFR mutation and ALK statuses prior to the use of TKIs in patients with adenocarcinoma." (PMID 33707479, 2021). "EGFR-mutant lung SCC has a worse prognosis than EGFR-mutant adenocarcinoma." (PMID 34195081, 2021). "Among all the driving gene mutations, the most common one is epidermal growth factor receptor (EGFR) gene mutation, especially for the patients in east Asia, non-smoking, women and adenocarcinoma." (PMID 33869057, 2021). "Transformation from adenocarcinoma to SCLC may originate from a minor preexistenting SCLC cell population under the selective pressure of EGFR-TKI treatment." (PMID 34397927, 2021). "Similarly, the vast majority of adenocarcinoma patients (39, 95.1%) received first- or second-generation EGFR-TKIs, only two (4.9%) received osimertinib." (PMID 34195081, 2021). "EGFR mutations were more frequently found in patients with confirmed adenocarcinoma (14/27, 51.8%) than in non-adenomatous NCSCL subtypes (3/14, 21.4%; p=0.03)." (PMID 33906297, 2021). "EGFR mutations were more common in female patients with adenocarcinoma, nonsmoker patients with NSCLC (P < 0.0001), and patients aged more than 40 years (P = 0.0196)." (PMID 33928034, 2021). "Rebiopsy might affect the clinical course of patients with EGFR‐mutant adenocarcinoma who receive EGFR‐TKIs." (PMID 33529490, 2021).
adenocarcinoma (continued). "Most studies have suggested that EGFR gene mutations were predominant in Asian nonsmoking women with adenocarcinoma, but gender was not an independent predictor of EGFR gene mutation in this study." (PMID 33314737, 2021). "Epidermal growth factor receptor (EGFR) mutations are found in ∼10%–12% of Caucasians with adenocarcinoma and are more frequent in never smokers, females and in patients of East Asian ethnicity." (PMID 33210237, 2021). "For example, epidermal growth factor receptor (EGFR) mutations are more frequently found in female patients who are never smokers and who have adenocarcinoma histology, whereas KRAS mutations are more common in adenocarcinoma patients who are smokers." (PMID 33707471, 2021). "This is the treatment option for adenocarcinomas without EGFR gain-of-function mutations or tumors that have developed resistance to targeted therapy." (PMID 34966671, 2021). "We suggest patients with NSCLC to be tested for EGFR mutations, especially those with adenocarcinoma regardless of clinical characteristics." (PMID 33906297, 2021). "All the 20 EGFR-mutated tumors were of adenocarcinoma histology and the patients with EGFR-mutated tumors were mainly women (16/20) and never-smokers (12/20)." (PMID 34625038, 2021). "With univariate survival analysis, many features were associated with outcome: age, gender, no- or light vs. heavy smoking, PS, TNM substages, pathological type adenocarcinomas vs. others, sum of TNM-PS-pathology, EGFR mutations, the number of PBT cycles and TKI-TT." (PMID 34993132, 2021). "Comparable to EGFR mutated NSCLC, conversion from adenocarcinoma to SCLC has been documented in a patient progressing on alectinib, thus confirming that histology transformation represents an escape mechanism in molecularly defined subgroups of NSCLC patients receiving a targeted agent." (PMID 33922215, 2021). "A total of 362 patients (98.4%) with EGFR-mutant NSCLC were diagnosed with adenocarcinoma." (PMID 34574036, 2021). "The fact that presence of EGFR mutation also multivariably was not significant can be due to the overshadowing prognostic significance of the pathology adenocarcinoma subtype." (PMID 34993132, 2021). "EGFR mutations are known to be associated with female gender, adenocarcinoma histology, and non-smoking status." (PMID 35008257, 2021). "In this study, sEVs were isolated from MPE fluid of four NSCLC patients, whose tumors were of adenocarcinoma histology and clinically validated to harbor EML4-ALK-fusion (PE002), KRAS-mutation (PE009), or mutations in the kinase domain of EGFR (PE011 and PE020)." (PMID 33671772, 2021). "Therefore, genetic testing, including at least EGFR mutations and ALK/ROS1 rearrangements, should be performed in all NSCLC patients (in particular with adenocarcinoma) who received a diagnosis of advanced disease." (PMID 34094913, 2021). "Some previous studies found that TMB in SCC was higher than that in adenocarcinoma, however, they did not distinguish between patients with EGFR mutations and those without EGFR mutations." (PMID 34195081, 2021). "According to the literature, 10–13% of Caucasian patients with adenocarcinoma (which represents the most part of non-squamous NSCLC) presents an EGFR activating mutation, 2–7% rearrangements of ALK and 1–4% BRAF mutations." (PMID 34885238, 2021). "Many studies showed that EGFR mutations are associated with adenocarcinoma, non-smokers, females, and Asians." (PMID 34963835, 2021). "Notably, these results were limited to the KRAS wild-type squamous cell carcinoma and adenocarcinoma, whereas in adenocarcinoma histotype the effect of epigenetic silencing of KEAP1 was also observed in the EGFR mutated subpopulation." (PMID 35004317, 2021).